U8 (U8 small nucleolar RNA )
Synonyms: LOC124900198
Gene: Small nucleolar RNA gene on chromosome 5 (68,873,954 to 68,874,087, forward strand). Ensembl gene ENSG00000212249.
Gene Ontology:
Biological process: RNA processing
Cellular component: nucleolus
Homologues: Orthologues: chimpanzee U8 (100% identical), macaque U8 (89% identical), pig U8 (60% identical). Paralogues in human: U8 (82% identical), U8 (81% identical), U8 (79% identical), U8 (78% identical), U8 (76% identical), U8 (75% identical), U8 (74% identical), U8 (72% identical), U8 (71% identical), U8 (68% identical), U8 (66% identical), U8 (64% identical), and 2 more.